ENPP1 (ectonucleotide pyrophosphatase/phosphodiesterase 1)
Diseases named in the same sentence as ENPP1 in open-access papers (continued):
Sharing a sentence is not in itself a finding about the gene and the disease.
rickets (continued). "Deficiency in ENPP1 enzyme function results in low levels of pyrophosphate (PPi) and adenosine monophosphate (AMP) leading to calcification of arteries, arterial stenoses, cardiac complications, and rickets/osteomalacia." (PMID 35895733, 2022). "This study also identified an ENPP1‐deficient population without GACI diagnosis with rickets (ARHR2)." (PMID 34355424, 2021). "In one consanguineous family with a homozygous c.797G>T nonsynonymous sequence variant in ENPP1, the father (Case 13) had rickets but no history of GACI, whereas his son (Case 14) presented with GACI in the first week of life and later exhibited hypophosphatemia." (PMID 35966073, 2022). "ENPP1 Deficiency—caused by biallelic variants in ENPP1—leads to widespread arterial calcification in early life (Generalized Arterial Calcification of Infancy, GACI) or hypophosphatemic rickets in later life (Autosomal Recessive Hypophosphatemic Rickets type 2, ARHR2)." (PMID 36461014, 2022). "In utero, findings such as pericardial effusion, polyhydramnios, cardiomyopathy and nonimmune hydrops fetalis may be indicative of ENPP1 Deficiency, especially in combination with family history of early fetal death or rickets." (PMID 36150100, 2022). "Eleven affected individuals were diagnosed with rickets or osteomalacia without a prior GACI or PXE diagnosis, a category designated as ARHR2; all had confirmed ENPP1 variants and median age (range) at diagnosis was 5.4 (2.2–54.5) years." (PMID 34355424, 2021). "Eleven affected individuals presenting with rickets and without a GACI diagnosis, termed autosomal recessive hypophosphatemic rickets type 2 (ARHR2), all had confirmed ENPP1 variants." (PMID 34355424, 2021).
autosomal recessive hypophosphatemic rickets type 2 (17 papers, 2019 to 2025). "In addition, ENPP1 Deficiency can result in Autosomal Recessive Hypophosphatemic Rickets Type 2 (ARHR2; OMIM #613,312) in those who survive GACI, or in individuals who never had clinical cardiovascular manifestations." (PMID 36461014, 2022). "The consequence of ENPP1 Deficiency is a broad range of age dependent symptoms and morbidities including cardiovascular complications and 50% mortality in infants, autosomal recessive hypophosphatemic rickets type 2 (ARHR2) in children, and joint pain, osteomalacia and enthesopathies in adults." (PMID 36150100, 2022). "Generalised arterial calcification of infancy (GACI) and autosomal recessive hypophosphatemic rickets type 2 (ARHR2) are caused by loss-of-function pathogenic variants in ENPP1." (PMID 41445557, 2025). "Natural history studies of patients with GACI due to ENPP1-deficiency indicate that many who survive the critical first year of life experience some resolution of arterial calcification but also can later develop autosomal recessive hypophosphatemic rickets type 2 (ARHR2; OMIM 613312)." (PMID 35482848, 2022). "Autosomal recessive hypophosphatemic rickets type 2 (ARHR2) is a rare form of hereditary rickets, which is characterized by defective bone mineralization and renal phosphate wasting due to a loss-of-function variant in the ectonucleotide pyrophosphatase/phosphodiesterase 1 (ENPP1) gene." (PMID 35966073, 2022). "In autosomal recessive hypophosphatemic rickets type 2 (ARHR2), ectonucleotide pyrophosphatase/phosphodiesterase family member 1 (ENPP1) fails to keep FGF23 levels low due to inactivating mutations in the ENPP1 gene resulting in hypophosphatemia." (PMID 35084563, 2022).
calcification (17 papers, 2005 to 2025). Process by which organic tissue becomes hardened by the physiologic deposit of calcium salts. "ABCC6 deficiency mainly causes PXE (MIM#264800), whereas defective ENPP1 (the key enzyme for PPi production) leads to generalized arterial calcification of infancy (GACI, MIM#208000)." (PMID 38392293, 2024). "Previous studies have shown that homozygous ENPP1 deficiency in humans leads to loss of enzyme activity and to a severe form of infantile arterial calcification." (PMID 37509127, 2023). "Reduced plasma PPi concentration, at approximately 0–10% of control subjects, is the basis for vascular calcification in ENPP1-deficiency." (PMID 35482848, 2022). "Periarticular calcification is a common attendant symptom of generalized arterial calcification of infancy, a rare Mendelian disorder caused by mutations of the gene coding for ectonucleotide pyrophosphatase/phosphodiesterase 1 (ENPP1)." (PMID 16207325, 2005). "ABCC6 and ENPP1 encode proteins that are required for the generation of inorganic pyrophosphate (PPi), a potent endogenous inhibitor of calcification, and pathogenic variants in both genes have been associated with syndromes of ectopic calcification." (PMID 35482848, 2022). "Deficiency of ENPP1 leads to generalized arterial calcification." (PMID 33101359, 2020). "Studies have associated treatment with bisphosphonates, chiefly etidronate, with improved survival in patients with GACI, an autosomal recessive disorder of spontaneous infantile arterial and periarticular calcification which is attributed to mutations in the ENPP1 gene." (PMID 25975272, 2015). "An unusual feature of ARHR type 2 is that mutations in ENPP1 are also associated with generalized arterial calcification of infancy, again the mechanism by which a mutation in ENPP1 can result in a disease characterised by hypomineralization and one characterised by hypermineralization is unknown." (PMID 21747952, 2011). "There is a similar prevalence of GACI phenotypes between ENPP1 and ABCC6 mutations, including arterial calcification (77.2% and 89.5%, respectively), organ calcification (65.8% and 84.2%, respectively), and cardiovascular complications (58.4% and 78.9%, respectively)." (PMID 38165475, 2024).
osteoporosis (15 papers, 2021 to 2025). A condition of reduced bone mass, with decreased cortical thickness and a decrease in the number and size of the trabeculae of cancellous bone (but normal chemical composition), resulting in increased fracture incidence. "The case presented in this article illustrates that the monoallelic inactivation mutations of the ENPP1 gene in the patient resulted in its inactivation, primarily manifesting as osteoporosis and bilateral slipped capital femoral epiphysis." (PMID 40270714, 2025). "Recent case reports have also linked ENPP1 heterozygous and compound heterozygous mutations to early-onset osteoporosis, DISH, and OPLL." (PMID 40535334, 2025). "The inactivating mutation of the ENPP1 single allele doesn’t cause death but can affect children’s growth, causing problems like delayed height development and early-onset osteoporosis." (PMID 40270714, 2025). "Humans with heterozygous loss of function pathogenic variants in ENPP1 develop early-onset osteoporosis." (PMID 38223929, 2024). "In our previous research, we found that Enpp1 deficiency causes mouse osteoporosis via the MKK3/p38 MAPK/PCNA signaling pathway." (PMID 37370114, 2023). "We also observed significant weight loss and worsening of osteoporosis in Enpp1 cKO mice under phosphate overload conditions, similar to global Enpp1-deficient mice." (PMID 38042486, 2023). "Humans with Enpp1 deficiency exhibit bone mineralization disturbances, resulting in early-onset osteoporosis." (PMID 36243801, 2022). "The inhibition of MKK3/p38 MAPK/PCNA pathway plays an important role in the development of osteoporosis caused by Enpp1 deficiency, and LPA partially rescued the proliferation of pre-osteoblasts via the MKK3/p38 MAPK/PCNA pathway." (PMID 36243801, 2022). "To explore the mechanism of early-onset osteoporosis induced by Enpp1 deficiency, we employed proteomics to analyze the protein profile of humeri from 12-week-old male WT and Enpp1 KO mice." (PMID 36243801, 2022). "Proteins from humeri and calvarial pre-osteoblasts (Pobs) were used to verify the differentially expressed signaling pathways and to explain the mechanism of Enpp1 deficiency-associated osteoporosis." (PMID 36243801, 2022). "We aimed to explore the changes in the signaling pathway expression of bone tissues involved in Enpp1 deficiency and reverse the phenotype of osteoporosis caused by Enpp1 deletion, and it will provide reference significance for future clinical work." (PMID 36243801, 2022). "Furthermore, monoallelic ENPP1 variants have been implicated in case reports of adults with early onset osteoporosis and fractures." (PMID 41445557, 2025). "A study pointed out that the heterozygous inactivated mutation of the ENPP1 gene could lead to bone mineralization defects and early-onset osteoporosis in patients." (PMID 40270714, 2025). "However, emerging evidence suggests that ENPP1 haploinsufficiency, even with a single functional allele, can also affect mineralization processes, contributing to early-onset osteoporosis, OPLL, and DISH." (PMID 40535334, 2025). "However, this changed in 2019 when Ralf Oheim at the University of Hamburg–Eppendorf Medical Center identified three patients with early-onset osteoporosis with heterozygous ENPP1 pathogenic variants." (PMID 37871131, 2024). "The clinical phenotypes induced by ENPP1 deficiency are seemingly contradictory and include early-onset osteoporosis in middle-aged adults and life-threatening vascular calcifications in the large arteries of infants with generalized arterial calcification of infancy." (PMID 37871131, 2024). "However, this study showed that vitamin D is a risk factor for ectopic calcification and osteoporosis when Enpp1 function is disrupted." (PMID 38042486, 2023). "Interestingly, Enpp1 deficiency can lead to osteoporosis and articular cartilage calcification, two antipodal fates." (PMID 37370114, 2023).
osteoporosis (continued). "While ENPP1 Deficiency is considered an autosomal recessive disorder, there are case reports of adults with monoallelic ENPP1 variants who presented with early‐onset osteoporosis and fractures." (PMID 36150100, 2022). "Apart from the current understanding of enzyme function, the mechanism of ectonucleotide pyrophosphatase/phosphodiesterase 1 (Enpp1) deficiency-associated osteoporosis is unknown." (PMID 36243801, 2022). "It is intriguing that heterozygous carriers of ENPP1 mutations are prone to osteoporosis." (PMID 34760935, 2021). "Although osteoporosis in patients with heterozygous ENPP1 pathogenic variants demonstrates a critical role for the enzyme in normal skeletal development, the mechanism by which ENPP1 regulates bone mass is unknown." (PMID 37871131, 2024). "The phenotypes of heterozygous carriers of ENPP1 pathogenic variants have not been well studied, but some researchers have suggested that mild hypophosphatemia, early-onset osteoporosis, or ossification/hyperostosis of the spinal ligament could be associated with ENPP1 haploinsufficiency." (PMID 35966073, 2022). "We show that conditions observed with high caloric intake, including ectopic calcification in kidney and osteoporosis, are also seen in Col2 Cre/Enpp1 cKO mice fed an HPD." (PMID 38042486, 2023). "Relative to WT controls, Enpp1 cKO mice exhibited phenotypes resembling human aging, such as short life span, ectopic calcifications, and osteoporosis, as well as significantly lower serum pyrophosphate levels." (PMID 38042486, 2023). "The allelic frequency of previously reported pathogenic variants of ENPP1 (rs2273411, rs20159006, rs148462924, rs147346173) detected in patients with OPLL or early-onset osteoporosis was as high as 0.5%." (PMID 37530996, 2023). "In this study, male Enpp1 KO mice were confirmed to be an animal model of early-onset osteoporosis through phenotypic trait assessment, including reduced body weight and lower bone mass." (PMID 36243801, 2022). "However, the molecular mechanism by which Enpp1 loss leads to osteoporosis remains unclear." (PMID 36243801, 2022). "Here, we report that Col2 Cre/Enpp1 cKO mice fed a HPD as adults show various phenotypes characteristic of normal aging, such as ectopic calcification of kidney and osteoporosis." (PMID 38042486, 2023). "Importantly, BMSCs isolated from patients with osteoporosis showed a decrease in histone H3K18la lactylation and the expression of the target genes COL1A2, COMP, ENPP1, and TCF7L2." (PMID 37752768, 2023). "qPCR analysis of the target genes of H3K18la lactylation indicated that the expression of the osteogenic genes COL1A2, COMP, ENPP1, and TCF7L2 was decreased in BMSCs isolated from patients with osteoporosis compared with that in BMSCs from patients without osteoporosis." (PMID 37752768, 2023).
hypophosphatemia (13 papers, 2014 to 2025). Lower than normal levels of phosphates in the circulating blood. "Human genetic studies linking ENPP1 mutations to increased FGF23 levels and subsequent hypophosphatemia have recently been confirmed in an Enpp1−/− mouse model." (PMID 24906371, 2014). "Because PHEX, DMP1, and ENPP1 all induce FGF23-related hypophosphatemia, they may affect common pathophysiological mechanisms inducing enthesopathies and spinal ligament ossifications." (PMID 37530996, 2023). "Some studies have suggested that an inverse correlation between the degree of hypophosphatemia of ARHR2 and aberrant calcification of GACI might exist, indicating that low phosphate levels may protect the ENPP1-deficient patients from pathologic arterial calcification." (PMID 35966073, 2022). "In ARHR2, in contrast to ENPP1-related GACI, a significantly stronger hypophosphatemia is found, which possibly represents a “protective mechanism” against arterial calcification." (PMID 34910242, 2022).
lung carcinoma (10 papers, 2017 to 2025). "In breast and lung cancer patients, increased ENPP1 expression was associated with cancer progressing from primary to the metastatic stage, suggesting an immune escape strategy as it leads to reduced T cell infiltration." (PMID 36235254, 2022). "Our studies suggest that breast and lung cancer release ENPP1‐positive exosomes into the tumor microenvironment to counter the anti‐tumor immunity." (PMID 38498770, 2024). "In the study of lung cancer, it was found that when ENPP1 gene was knocked out in lung cancer cell lines, the expression of a large number of stem cell markers decreased, including ABCG2, SOX2, NANOG, and CD44." (PMID 33635867, 2021). "Further, they detected the ENPP1 expression in several lung cancer cell lines (including H1792, A549 and HCC827) and found that ENPP1 was also highly expressed." (PMID 33635867, 2021). "Indeed, we observed high expression of ENPP1 in exosomes from breast and lung cancer tissue samples, and tumor exosomal ENPP1 inhibited the immune infiltration of CD8+ T cells and CD4+ T cells." (PMID 38498770, 2024). "Furthermore, high expression of ENPP1 in exosomes is observed isolated from human breast and lung cancer tissue, and tumor exosomal ENPP1 inhibited the immune infiltration of CD8+ T cells and CD4+ T cells." (PMID 38498770, 2024). "We first surveyed ENPP1 protein expression in primary skin cutaneous melanoma (SKCM), ductal carcinoma of the breast (DCIS), non‐small cell lung cancer (NSCLC), colorectal cancer (COAD), and glioma by immunohistochemical (IHC) staining experiments." (PMID 38498770, 2024). "Notably, the lung cancer cell line LLC did not express Enpp1; however, analysis of lung cancer cell lines from human tumors demonstrated that these generally express Enpp1." (PMID 39622844, 2024).
osteomalacia (8 papers, 2019 to 2025). Disorder caused by an interruption of the mineralization of organic bone matrix leading to bone softening, bone pain, and weakness. "The adult form of ENPP1 Deficiency has similar characteristics to the pediatric form, including skeletal deformities, osteomalacia, osteoarthritis, and interosseous membrane ossification." (PMID 35895733, 2022).
ankylosis (7 papers, 2013 to 2025). Fixation and immobility of a joint. "Ectonucleotide pyrophosphatase/phosphodiesterase 1 (ENPP1) catalyzes the conversion of Pi to PPi, and progressive ankylosis gene product (ANK) catalyzes the reverse reaction." (PMID 39199142, 2024). "However, on a high Pi diet, Enpp1−/− mice developed ankylosis, which was eliminated when mice were administered an ENPP1‐Fc protein that restored PPi levels and decreased hypercementosis." (PMID 35460154, 2022). "For HA synthesis, alkaline phosphatase (ALP) hydrolyses pyrophosphate (PPi) to inorganic phosphate, ectonucleotide pyrophosphatase/phosphodiesterase 1 (ENPP1) synthesizes PPi, and ankylosis human (ANKH) transports PPi to the extracellular matrix where HA is formed." (PMID 29194391, 2017).
myocardial infarction (7 papers, 2012 to 2025). Gross necrosis of the myocardium, as a result of interruption of the blood supply to the area, as in coronary thrombosis. "Antibodies that target ENPP1 to prevent its enzymatic activity have been developed and tested in preclinical models of myocardial infarction to limit the cell death and fibrosis that is linked to increased ENPP1 activity following cardiac injury." (PMID 40519286, 2025). "After myocardial infarction, the ectonucleotidase ENPP1 initiates an aberrant metabolic cascade that disrupts nucleotide biosynthesis and worsens heart repair." (PMID 39454569, 2024). "Recombinant human ENPP1-Fc protein administration inhibits VSMC proliferation, showing efficacy in preventing aortic calcification and myocardial infarction in mouse models with ENPP1 deficiency." (PMID 38542110, 2024). "According to research, administering soluble recombinant human ENPP 1-Fc protein can prevent myocardial infarction and aortic calcification in mouse models that have ENPP 1 deficiency." (PMID 38248755, 2023).
Hyperglycemia (6 papers, 2014 to 2022). An increased concentration of glucose in the blood. "Transgenic mice over-expressing the human ENPP1 driven by the CMV promoter had hyperglycemia and hyperinsulinemia with impaired glucose tolerance test, and reduced glucose uptake in the muscle." (PMID 29513794, 2018). "Thus, our observed increased expression of both these genes (ENPP1 and ESP) is consistent with the HYP mice hyperglycemia and altered insulin sensitivity." (PMID 24839967, 2014).
Hypertension (6 papers, 2012 to 2025). The presence of chronic increased pressure in the systemic arterial system. "In this study, we presented a case of an adolescent with an ENPP1 mutation who complained of uncontrolled hypertension." (PMID 37153460, 2023). "The patient presented with severe hypertension and seizures, which revealed diffused calcifications and c.130C > T and c.1112A > T mutations in the ENPP1 gene." (PMID 35003211, 2021). "We report a case of neonatal GACI: clinical presentation was a severe early-onset hypertension, investigations found diffuse calcifications on imaging and a mutation in ENPP1 gene." (PMID 29976176, 2018). "In this study, we demonstrate, for the first time, that ENPP1 replacement therapy can significantly reduce both arterial calcification and hypertension in a mouse model of GACI." (PMID 30158213, 2018). "ENPP1-Fc fusion protein administration to mice models of GACI has been shown to eliminate cardiac and arterial calcifications, reduce hypertension, prevent the formation of neointimal proliferation and improve survival." (PMID 41445557, 2025). "This study suggests that ENPP1 enzyme replacement therapy could be a more effective GACI therapeutic than bisphosphonates, treating not just the vascular calcification, but also the hypertension that eventually leads to cardiac failure in GACI patients." (PMID 30158213, 2018).